NTN1 (netrin 1)
Diseases named in the same sentence as NTN1 in open-access papers (continued):
Sharing a sentence is not in itself a finding about the gene and the disease.
Insulin resistance (19 papers, 2016 to 2025). Increased resistance towards insulin, that is, diminished effectiveness of insulin in reducing blood glucose levels. "Further, a clinical investigation has revealed that levels of circulating netrin-1 are positively associated with critical markers such as fasting blood glucose, HbA1c levels, and the insulin resistance index." (PMID 40405979, 2025). "Emerging biomarkers associated with insulin resistance include netrin 1 (Ntn-1), a cell migration guidance protein comprising 640 amino acids." (PMID 40004236, 2025). "These include the observations that netrin-1 dampens inflammatory peritonitis in vivo and that netrin-1 expression in the adipose tissue of obese individuals favours macrophage retention, characteristic of chronic inflammation and insulin resistance associated with type 2 diabetes." (PMID 27509208, 2016). "Recent studies have identified a correlation between elevated serum levels of Ntn-1 and patients with insulin resistance and T2D." (PMID 40004236, 2025). "Our findings indicate that Netrin-1 and adiponectin exhibit opposing patterns in the context of metabolic inflammation and insulin resistance." (PMID 40949120, 2025). "Netrin-1 levels were reduced in the plasma of T2D patients, showing an inverse relationship with insulin resistance." (PMID 35498433, 2022). "Although inflammation is a major contributing factor in the development of insulin resistance and type 2 diabetes, little is known about a possible relationship between serum netrin-1 and type 2 diabetes." (PMID 30532735, 2018). "The high expression of Netrin-1 supports defective adipose tissue migration and retention which, in turn, enhance the progression of chronic inflammation, insulin resistance, and metabolic dysfunction." (PMID 30320139, 2018). "Serum netrin-1 levels were significantly positively correlated with fasting glucose, HbA1c, and insulin resistance index (all Ps < 0.01)." (PMID 30532735, 2018). "Urinary netrin-1 excretion appears to be affected predominantly by insulin resistance and hyperinsulinemia." (PMID 27087488, 2016). "Additionally, the extent of Netrin-1 was found to be inversely related to the homeostasis model evaluation of insulin resistance and plasma glucose (fasting and post-meal), fasting insulin, triglyceride, and hemoglobin A1c levels." (PMID 34179515, 2021). "Additionally, the extent of Netrin-1 was found to be inversely related with homeostasis model evaluation of insulin resistance and plasma glucose (fasting and post-meal), fasting insulin, triglyceride, and hemoglobin A1c levels." (PMID 30320139, 2018). "Insulin resistance and hyperinsulinemia seem to be related to the urinary level of netrin-1." (PMID 27087488, 2016). "If supplied with exogenous netrin-1 to patients could increase insulin sensitivity and improve insulin resistance." (PMID 27255377, 2016). "Therefore, we hypothesize that the immunomodulatory activities of Ntn1 might play an important role in the pathogenesis and development of insulin resistance, as well as in the onset of and complications related to T2D." (PMID 36661496, 2022). "Urinary netrin-1 level was significantly higher in obese subjects with insulin resistance compared to those without insulin resistance (1142±1181 vs. 604.9±589.91 pg/mg creatinine, p=0.001)." (PMID 27087488, 2016). "In addition, contrary to our observations, they showed higher urinary netrin-1 in children with insulin resistance compared to those without these disorders." (PMID 39409098, 2024). "Furthermore, we found that urinary netrin-1 level was higher in normotensive obese subjects with insulin resistance when compared to those without insulin resistance." (PMID 27087488, 2016). "However, urinary netrin-1 was significantly higher in patients with insulin resistance than patients without insulin resistance [645.6 (480.4-1012.5) vs. 431.3 (207.2-682.5) pg/mg creatinine, p=0.005]." (PMID 27087488, 2016).
Stroke (19 papers, 2015 to 2025). Sudden impairment of blood flow to a part of the brain due to occlusion or rupture of an artery to the brain. "So, we speculate that the activation of the JNK1 pathway may be the potential underlying mechanism for the Netrin-1-induced protective effects after stroke." (PMID 29487502, 2018). "In experimental stroke models, exogenous netrin-1 administration reduces infarct size, enhances microvascular density, and suppresses leukocyte infiltration." (PMID 41303115, 2025). "At the same time, there have been links reported between stroke outcomes and metabolic regulators like omentin-1, neurotrophic and angiogenic modulators like netrin-1, and oxidative stress markers like thioredoxin." (PMID 41303115, 2025). "It discusses the multifaceted role of Netrin-1, highlighting its potential in promoting neurovascular repair and mitigating post-stroke neurological decline." (PMID 38672167, 2024). "This study aimed to assess rTMS’s effect on post-stroke endogenous neuroplasticity by dosing plasma miRs 17~92, Netrin-1, Sema3A, and BDNF." (PMID 38540283, 2024). "Our findings indicate that Netrin-1 enhances microglia migration, further highlighting its therapeutic potential in stroke." (PMID 39000184, 2024). "Evidence suggests that Netrin-1 is crucial in promoting axonal regeneration, synaptic remodeling, neural stem cell migration, and white matter repair across various stroke models." (PMID 38672167, 2024). "Recent studies have explored the potential of Netrin-1 in stroke treatment, suggesting its ability to inhibit microglia activation and inflammation cytokine release in a hemorrhagic stroke rat model." (PMID 39000184, 2024). "In models of subarachnoid hemorrhage, multiple sclerosis, and stroke, NTN-1 has been shown to have a protective effect on the BBB and to improve neurocognitive function, which was also noted in our model." (PMID 35095412, 2021). "This extends findings from previous studies: netrin-1 seals endothelial barriers like the blood–retina barrier in diabetic retinopathy as well as the BBB in stroke, hemorrhage, and experimental autoimmune encephalomyelitis." (PMID 34576252, 2021). "Data in the present study indicate a robust effect of combined XSEC and EE on up-regulating the protein expression levels of Netrin-1 and Robo-1 in the peri-ischemic brain tissues after stroke." (PMID 31354412, 2019). "In our study, we found that after stroke, Netrin-1 overexpression increased the expression level of both SYN and PSD-95, indicating that Netrin-1 can promote synaptic formation in both the pre-synaptic and post-synaptic region." (PMID 29487502, 2018). "The study also found that Netrin-1 promoted neural functional recovery, synaptic formation and axonal regeneration in the subacute stage of stroke, and that the inhibition of JNK1/c-Jun pathway partly abolished these effects." (PMID 29487502, 2018). "As a secreted axon guidance molecule, Netrin-1 has been documented to be a neuroprotective factor, which can reduce infarct volume, promote angiogenesis and anti-apoptosis after stroke in rodents." (PMID 29487502, 2018). "To further explore the effect of Netrin-1 on synaptic formation and its intrinsic mechanism after the experimental stroke, we first analyzed the expression of pre-synaptic protein, SYN, and post-synaptic protein, PSD-95." (PMID 29487502, 2018). "In accordance with previous studies, the results of the current study suggest that Netrin-1 can facilitate neural functional recovery and reduce neural impairment after stroke." (PMID 29487502, 2018).
Stroke (continued). "Netrin-1, secreted by microglia, regulates their apoptotic capabilities, promotes M2-like transformation, and inhibits apoptosis, all of which aid in tissue repair following a stroke." (PMID 40723793, 2025). "Combining vascular and trophic biomarkers (netrin-1, omentin-1, and circRNAs) with injury markers (NfL) and oxidative stress indicators (thioredoxin and bilirubin) moves stroke assessment beyond lesion quantification to evaluating repair capacity and systemic resilience." (PMID 41303115, 2025). "Therefore, the anti-apoptotic strategy mediated by Netrin-1 holds significant potential for developing novel stroke therapies." (PMID 38672167, 2024). "Sema3A and Ntn-1 participate in post-stroke brain remodeling in rats." (PMID 38540283, 2024). "We also measured levels of Ntn-1 and Sema3A as peripheral markers for post-stroke axogenesis." (PMID 38540283, 2024). "Evidence suggests that Netrin-1 may be a promising drug candidate for reducing stroke severity and improving prognosis, and its neuroprotective mechanisms may be achieved through regulation of angiogenesis, autophagy, apoptosis, and neuroinflammation." (PMID 35493300, 2022). "Subsequently, evidence revealed that Netrin-1 could induce angiogenesis and improve the post-stroke neurovascular structure in adult mouse brains." (PMID 35559236, 2022). "Netrin-1 stimulates endothelial cell proliferation and migration in vitro, and induces angiogenesis and improves post-stroke neurovascular structure in adult mouse brains which may contribute to long-term functional outcome after ischemic injury." (PMID 31354412, 2019). "Itga3 as a proposed receptor for Netrin-1 might facilitate and enhance cell-contact-dependent axon guidance within the stroke-denervated hemicord." (PMID 30962276, 2019). "Previous studies demonstrate that Netrin-1 facilitates angiogenesis and long-term neurological recovery, decreases the infarct size, improves spatial memory and synaptic plasticity, and promotes anti-apoptosis after stroke." (PMID 29487502, 2018). "Furthermore, the results of quantitative analysis of synapses indicate that Netrin-1 promotes PSD reconstruction after stroke via mediating PSD thickness, PSD area and width of the synaptic cleft." (PMID 29487502, 2018). "Therefore, we speculate that Netrin-1 can promote neural functional recovery after stroke by activating the JNK1 signaling pathway." (PMID 29487502, 2018). "Thus, the beneficial effects of ADSC transplantation on promoting angiogenesis after stroke may involve netrin-1 in the repair and re-establishment of the vascular network in the peri-infarct cortex." (PMID 29017609, 2017). "In this study, we identified Netrin-1 and CXCL12 as important factors that were involved in the OPC related post-stroke recovery." (PMID 34881088, 2021). "Individual genes from these pathways, including Netrin-1 and TGF-beta-1 were found to have increased expressions after neurological damage after stroke." (PMID 26675167, 2015). "Meanwhile, axonal guidance signaling Netrin-1 and Robo-1 would be expected to participate in the beneficial effects of the combined actions of XSEC and EE on angiogenesis and neurogenesis in the ischemic brain after stroke." (PMID 31354412, 2019). "Additionally, the effects of Netrin-1 on synapses were partly abolished by SP600125, suggesting that the JNK1/c-Jun pathway mediates Netrin-1-induced synaptic formation after stroke." (PMID 29487502, 2018). "In addition, netrin-1 and its receptors DCC and Unc5B have been demonstrated to be involved in the exercise-induced functional recovery of rats after stroke." (PMID 29017609, 2017).
type 2 diabetes (18 papers, 2016 to 2026). "Serum netrin-1 was also independently associated with IFG or type 2 diabetes after adjusting for covariates and potential confounders." (PMID 30532735, 2018). "In conclusion, we report that elevated serum netrin-1 levels are significantly associated with IFG or newly diagnosed type 2 diabetes." (PMID 30532735, 2018). "After adjusting for sex, age, BMI, fasting plasma glucose, HbA1c, ALT, HDL cholesterol, eGFR, and statin use, IFG or type 2 diabetes was independently associated with serum netrin-1 levels (standardized [STD] β = 0.405, P < 0.001; Model 2)." (PMID 30532735, 2018). "The use of a cutoff value of 324.9 pg/mL for serum netrin-1 was associated with the highest value to predict IFG or type 2 diabetes with a sensitivity and specificity of 80.2% and 73.2%, respectively." (PMID 30532735, 2018). "Serum netrin-1 levels were independently associated with IFG or type 2 diabetes (standardized β = 0.405, P < 0.001) after adjusting for covariates and potential confounders." (PMID 30532735, 2018). "Therefore, we investigated the association between circulating levels of netrin-1 and glycometabolic parameters predictive of type 2 diabetes." (PMID 30532735, 2018). "This system was able to disrupt the Ntn1 gene specifically in macrophages and their precursor monocytes in vivo, reducing netrin-1 expression and improving type 2 diabetes symptoms in a mouse model." (PMID 39201574, 2024). "Due to the cross-sectional design of the study, we cannot infer a causal relationship between an increased netrin-1 concentration and IFG or early stage of type 2 diabetes." (PMID 30532735, 2018). "We measured circulating levels of netrin-1 and other laboratory parameters at the time of diagnosis of type 2 diabetes, showing mean values of HbA1c 6.8% and HOMA-IR 4.90." (PMID 30532735, 2018). "Compared to normal controls mean serum netrin-1 levels were significantly higher in subjects with type 2 diabetes or IFG (441.0 pg/mL, 436.6 pg/mL and 275.9 pg/mL, respectively; P for trend < 0.001)." (PMID 30532735, 2018). "Multivariable-adjusted regression analyses were conducted to investigate the independent association between serum netrin-1 level and IFG or type 2 diabetes." (PMID 30532735, 2018). "Serum netrin-1 concentrations were significantly higher in individuals with IFG or type 2 diabetes, and serum netrin-1 level was significantly positively correlated with fasting glucose, HbA1c, HOMA-IR, AST, and ALT." (PMID 30532735, 2018). "The overexpression of Netrin-1 in ADSCs improves proliferation, migration, and treatment effect in type 2 diabetic mice with sciatic denervation, which directs the clinical treatment of patients with DPNVs." (PMID 30359296, 2018). "Further prospective studies are needed to elucidate the role of netrin-1 in the pathogenesis of type 2 diabetes and expand its potential for diagnosis and treatment." (PMID 30532735, 2018). "Liu and colleagues showed that in patients with newly diagnosed type 2 diabetes, netrin-1 levels were significantly lower than in normal controls." (PMID 30532735, 2018). "Netrin 1 (Ntn1) is a cell migration protein with an anti-inflammatory effect, which may play a key role in the pathological development of type 2 diabetes (T2D)." (PMID 36661496, 2022). "In the previous report, mean circulating levels of netrin-1 were 1.77 pg/mL in normal controls and 0.96 pg/mL in patients with type 2 diabetes, but 275.9 pg/mL in normal controls and 441.0 pg/mL in patients with type 2 diabetes in our study." (PMID 30532735, 2018). "Therefore, we investigated circulating levels of netrin-1 and its associations with clinical parameters in three population groups: normal controls and individuals with IFG and type 2 diabetes." (PMID 30532735, 2018). "This suggests that netrin-1 may be a sensitive indicator for early type 2 diabetes." (PMID 35008701, 2021).
type 2 diabetes (continued). "This perspective of netrin-1 as a modulator of inflammatory response and regeneration in pancreas, endogenous circulating netrin-1 may be implicated in the pathophysiologic mechanism of IFG or type 2 diabetes." (PMID 30532735, 2018). "Multivariable-adjusted regression analysis of the correlation between serum netrin-1 levels and IFG or type 2 diabetes (n = 218)." (PMID 30532735, 2018). "When we compared netrin-1 levels according to glycemic status, we found that values were higher in individuals with IFG and highest in patients with type 2 diabetes compared with healthy controls." (PMID 30532735, 2018). "Second, we identified serum netrin-1 levels as a possible predictor of both IFG and type 2 diabetes." (PMID 30532735, 2018). "This notion, coupled with the tissue regenerative and immunomodulatory properties of netrin-1, led us to explore whether circulating levels might be related to the development of IFG or type 2 diabetes." (PMID 30532735, 2018). "Moreover, investigation of the mechanism of action between netrin-1 level and pathogenesis of IFG and early stage of type 2 diabetes is needed to further our understanding." (PMID 30532735, 2018). "Finally, we conducted multivariable-adjusted regression analyses to investigate the independent relationships between netrin-1 level and IFG or type 2 diabetes adjusting for potential confounders, including eGFR and HOMA-IR." (PMID 30532735, 2018). "The present study demonstrates, for the first time, that serum netrin-1 level may serve as a sensitive and early indicator of the development of IFG and type 2 diabetes." (PMID 30532735, 2018). "In the present study, serum netrin-1 was significantly elevated in individuals with IFG or type 2 diabetes compared to normal controls, which is probably attributable to a compensatory response to IFG or type 2 diabetes." (PMID 30532735, 2018). "Therefore, future studies with type 2 diabetes model should be performed with a more detailed experimental design by focusing on the dose-dependent effect of CMD as well as the direct interaction between CMD and netrin-1 or other targets." (PMID 38628640, 2024). "Although mean HbA1c values were 6.8% in newly-diagnosed drug-naïve patients with type 2 diabetes and 5.9% in individuals with IFG, we found grade-dependent levels of serum netrin-1 according to group, suggesting netrin-1 may be a sensitive indicator for IFG or early type 2 diabetes." (PMID 30532735, 2018). "In addition, the receiver operating characteristic (ROC) analysis showed that serum netrin-1 levels could identify the presence of IFG and type 2 diabetes with the area under the ROC curve (AUC) of 0.784 (P < 0.001)." (PMID 30532735, 2018).